EGFR (epidermal growth factor receptor)
Diseases named in the same sentence as EGFR in open-access papers (continued):
Sharing a sentence is not in itself a finding about the gene and the disease.
glioblastoma (continued). "At the molecular level, EGFR siRNA was abundantly present in glioblastomas of mice treated with the CMV-RVG-siRE or CMV-RVG-siRE+T circuit, whereas EGFR protein levels were significantly reduced." (PMID 33782530, 2021). "Kinase-activating mutations lead to increased tyrosine kinase activity in EGFR and are frequently present in NSCLC and glioblastoma but rarely in other types of cancers." (PMID 34069119, 2021). "Amplification of the EGFR gene and subsequent over-expression of EGFR protein is a common genetic alteration in primary glioblastoma, with a frequency of approximately 40%." (PMID 33801941, 2021). "For example, the combination of histone deacetylase (HDAC) inhibitor + EGFR inhibitor can prevent the development of the resistance in glioblastoma cells." (PMID 34638714, 2021). "The amplification of LANCL2 or EGFR, and their co-amplification were frequent in glioblastoma of TCGA database and our tumor banks." (PMID 34461927, 2021). "Primary NK cells transduced with EGFR-CAR also showed enhanced cytotoxicity against patient-derived glioblastoma cell lines in-vitro." (PMID 33923528, 2021). "In Lee’s dataset, the expression of EGFR was 3.772 times higher in glioblastoma tissues than in normal tissues." (PMID 33892666, 2021). "Among these genes, EGFR is recognized as a driving receptor tyrosine kinase (RTK) in glioblastoma and induces multiple oncogenic signaling, which accounts for approximately 60% of glioblastoma cases." (PMID 33525678, 2021). "This evidence indicated that the observed survival benefit of misclassified histological grade 4 IDH-wildtype glioblastoma was due more to the model’s prediction than + 7/ − 10 or EGFR amplification status." (PMID 34863298, 2021). "By comparing 790 human glioblastomas, the authors reported NFKBIA deletion in glioblastoma to result in clinical outcomes comparable to EGFR amplification." (PMID 34440811, 2021). "HCT116 ATG16L1 T300 colon cancer cells and GBM6 cells, a PDX glioblastoma isolate expressing truncated EGFR vIII, were transfected with a plasmid to express LC3-GFP-RFP and with siRNA molecules to knock down expression of AMPKα1 or eIF2α." (PMID 34252884, 2021). "‘Common’ CNAs were found in chromosomes 7 and 10, of which the most frequent putative glioblastoma drivers, such as EGFR, CDK6, MET, and PTEN, are located." (PMID 33477674, 2021). "Previous studies have found that ADCs specifically targeting EGFR demonstrated promising therapeutic efficacy in some solid tumors, such as colorectal cancer and glioblastoma multiforme." (PMID 34879870, 2021). "Phosphoproteome analysis identified the epidermal growth factor receptor (EGFR) signaling axis commonly hyperactive in glioblastoma to depend on Lpd." (PMID 34771501, 2021). "Inhibition of DYRK1A in glioblastoma stem cell induces degradation of epidermal growth factor receptor (EGFR), resulting in decreased self-renewal of EGFR-addicted cells." (PMID 33863878, 2021). "In particular, KNE, an oHSV retargeted to human EGFR, significantly increased the survival of mice orthotopically injected with human glioblastoma cells and was able to cure about 70% of treated animals." (PMID 34578259, 2021). "EGFR, VEGF and RET tyrosine kinase are shown to be a contributing factor in the underlying drug-resistance mechanisms in glioblastoma patients." (PMID 33525678, 2021). "EGFR alterations are more commonly observed in patients with glioblastomas (GBM) in comparison to low-grade gliomas." (PMID 35601813, 2021).
glioblastoma (continued). "Amplification of the epidermal growth factor receptor (EGFR) gene is known to be observed in more than 50% of glioblastoma cases." (PMID 34685455, 2021). "Similar changes in EGFR expression have also been observed in glioblastoma cells as well as in squamous cell carcinoma to increase growth factor-induced tumor invasion." (PMID 34965432, 2021). "The mutual interaction between FPRs and EGFR aggravates the tumorigenicity of the glioblastoma cells." (PMID 34650406, 2021). "Using a fluorescent reporter for cell surface receptor distribution during mitosis, we found that ACD generated a daughter cell with enhanced therapeutic resistance and increased coenrichment of EGFR and neurotrophin receptor (p75NTR) from a glioblastoma CSC." (PMID 33351787, 2021). "MV was also designed to express interleukin-13 (IL-13) directed to the IL-13Rα2 receptor on glioblastoma (GBM) cells, or the single-chain antibody versus the vIII variant of epidermal growth factor receptor (EGFRvIII)." (PMID 34439595, 2021). "Efforts are underway to retarget oncolytic RNA-based virus vectors to tumors cells with elevated expression of EGFR and the constitutively active EGFRvIII mutant associated with poor prognosis in multiple human cancers particularly glioblastoma multiforme (GBM)." (PMID 35083168, 2021). "Inhibition of DYRK1A promotes EGFR degradation in primary glioblastoma cell lines and neural progenitor cells, sharply reducing the self‐renewal capacity of normal and tumorigenic cells." (PMID 34109727, 2021). "Genomic alterations such as amplification of EGFR gene or mutation and methylation of PTEN tumor suppressor gene have been observed in 50–70% of glioblastoma cases and correlate with the deregulation of the PI3K/Akt pathway." (PMID 34439380, 2021). "It has been demonstrated that chlorotoxin binds to most primary glioblastoma tumors, whereas antibodies to Her2, IL13Rα2, or EGFR binds to a small population of primary glioblastoma tumors." (PMID 34209505, 2021). "Data from PLA demonstrated that oxelaidin suppresses interactions between RRAD and EGFR or STAT3 in glioblastoma cells, supporting its utility as an active anti-glioma agent." (PMID 33980886, 2021). "They had important medical significance because the truncated EGFR occurred frequently in glioblastoma, breast, lung and ovarian cancer." (PMID 33407085, 2021). "A large percentage of glioblastomas are resistant to temozolomide due to the coactivation of the epidermal growth factor receptor (EGFR) family and receptor tyrosine kinase proteins, including mesenchymal‐epithelial transition factor (MET)." (PMID 34085418, 2021). "The fMLF rapidly induces EGFR phosphorylation at tyrosine residue 992, which contributes to the biological function of FPRs in the glioblastoma cells." (PMID 34650406, 2021). "In WHO CNS5, EGFR gene amplification is a criterion to upgrade IDH-wildtype diffuse astrocytic tumors in adults to glioblastoma, IDH-wildtype." (PMID 34827431, 2021). "In particular, the epidermal growth factor receptor (EGFR) is a primary driver of glioblastoma tumorigenesis, contributing mainly to cell proliferation and invasion." (PMID 34316711, 2021). "The RTK subgroups accounted for 63.2% of the glioblastoma IDH-wild-type cases, and the EGFR subgroup alone, for 41.4%, being thus the largest of all glioblastoma molecular subgroups." (PMID 34572759, 2021). "For a diagnosis of “Glioblastoma, IDH-wildtype” the novel WHO CNS5 incorporates 3 genetic parameters (TERT promoter mutation, EGFR gene amplification, combined gain of entire chromosome 7 and loss of entire chromosome 10) as criteria." (PMID 35008238, 2021).
glioblastoma (continued). "WTAP, another member of m6A writer, enhances proliferation, migration, invasion, and tumorigenicity of glioblastoma cells in xenotransplantation by mediating the phosphorylation of epidermal growth factor receptor (EGFR) and AKT." (PMID 33658391, 2021). "CD44 depletion collectively with EGFR inhibition results in synergistic and robust glioblastoma cell death." (PMID 34944493, 2021). "On top of that, in WHO CNS5 EGFR gene amplification is one of the criteria to upgrade IDH-wildtype diffuse astrocytic tumor in adults to glioblastoma, IDH-wildtype." (PMID 34638714, 2021). "MAPK is another oncogenic module downstream of EGFR that induces cell mobility and migration in glioblastoma cells." (PMID 35194440, 2021). "miR-7 has shown anti-proliferative effects in many cancers through its target oncogenes such as AKT in hepatocellular carcinoma, EGFR in glioblastoma (GBM), and PAX6 in colorectal cancer." (PMID 34162394, 2021). "Unfortunately, the addition of Depatux-M to standard chemo-irradiation with TMZ in newly diagnosed EGFR amplified glioblastoma patients was eventually discontinued for futility." (PMID 34926242, 2021). "The efforts for molecularly classifying glioblastoma have been recently reviewed and are based on a bioinformatics study categorizing in three different clusters the tumors with EGFR, NF1, and PDGFRA/IDH genetic alterations." (PMID 34572759, 2021). "A specific EGFR mutation, known as EGFR variant III mutation, was detected in glioblastoma tissue in the initial phase as well as in relapse, although in the latter frequency was lower than in tumor tissue from the initial surgery." (PMID 34439613, 2021). "The reappearance of the wildtype EGFR in recurrent glioblastoma precludes further treatment with Rindopepimut targeting EGFRvIII." (PMID 34485282, 2021). "In conclusion, our findings revealed that miR-142 has therapeutic potential via suppressing glioblastoma cell growth and invasion and can be used as a regulator of oncogenic EGFR signaling pathway as well." (PMID 35194440, 2021). "For example, chromosomal mutant of the epidermal growth factor receptor gene can make glioblastoma cells resistant to epidermal growth factor receptor inhibitors." (PMID 34496843, 2021). "Other studies are in concordance with our results and indicate a high frequency of EGFR gene amplification in 57.4% of glioblastomas." (PMID 34209611, 2021). "Regarding signal transduction, many of the interacting proteins mapped to frequently deregulated signaling pathways in glioblastoma such as the EGFR-MAPK, PI3K-AKT- mTOR and Small GTPase signaling hubs; a finding in line with our phosphoproteome analysis." (PMID 34771501, 2021). "DYRK inhibitors have previously demonstrated activity against human glioblastoma models through EGFR destabilization." (PMID 34708541, 2021). "ZEGFR:03115-IR700 showed significant activity in inducing cell death in EGFR-positive U87-MGvIII glioblastoma cells in vitro." (PMID 34203805, 2021). "In Bredel’s dataset, the expression of EGFR was 5.840 times higher in glioblastoma tissues than in normal tissues." (PMID 33892666, 2021). "The deletion mutant of EGFR with constitutively active tyrosine kinase activity (EGFRvIII) is common in glioblastoma and contributes significantly to cancer cell growth and survival." (PMID 34206547, 2021). "EGFR mutations are related to a number of important functions in cancers, including LUAD and glioblastoma, which regulate cell–cell adhesion division and cell differentiation." (PMID 34076361, 2021). "We then measured the expression of EGFR, a direct target of miR-491-5p in glioblastoma and ovarian cancer cells, and a predicted target of miR-342-5p." (PMID 34070455, 2021). "It was first identified in an ethylnitrosourea (ENU) induced rodent glioblastoma cell line and is highly homologous to the HER1 gene, which encodes the human epidermal growth factor receptor (EGFR)." (PMID 39035769, 2021).
glioblastoma (continued). "Specifically, for glioblastoma, EGFR, TERT, and +7/−10 cytogenetic signature are the molecular markers, and MGMT is a predictive biomarker of the benefit from alkylating chemotherapy." (PMID 33708196, 2021). "PI3K, EGFR, IDH1 and IDH2 mutations are examples of factors that alter the glioblastoma epigenome to confer increased growth and resistance to therapy." (PMID 34769339, 2021). "To clarify the hierarchical functionality of the Lpd-EGFR interplay further, we performed Western blot analysis of EGFR and Lpd expression as well as EGFR Y1068 and Lpd Y426 phosphorylation in the glioblastoma cell line panel." (PMID 34771501, 2021). "EGFR is a transmembrane cell surface receptor frequently overexpressed in patients with glioblastoma (GBM) that contributes to the formation of the tumor, meanwhile, EGFRvIII is the most common EGFR mutation in EGFR-positive patients with GBM." (PMID 34039409, 2021). "We therefore quantified by Western Blot the expression levels of wild type EGFR and EGFRvIII in three cultures of glioblastoma derived from different patients and maintained as glioblastoma initiating cells (hGICs, kindly provided by Dott." (PMID 34578259, 2021). "Schulte and coworkers showed that the presence of EGF in the culture media purges EGFR gene amplification from patient‐derived glioblastoma cells, largely decreasing their tumorigenicity in xenografts." (PMID 33955157, 2021). "Amplification of epidermal growth factor receptor (EGFR) and its active mutant EGFR vIII occurs frequently in glioblastoma and their expression levels are correlated with poor prognosis of glioma patients." (PMID 33980886, 2021). "VOPP1, also known as glioblastoma-amplified secreted protein and EGFR-coamplified and overexpressed protein (ECOP), is upregulated in multiple human tumors, such as gastric cancer and squamous cell carcinoma." (PMID 34708039, 2021). "Other reports with 45% of glioblastomas having EGFR gene amplification are also consistent with our data." (PMID 34209611, 2021). "Tumorigenicity is preferentially augmented in glioblastoma via activation of STAT3 whereas EGFR contributes to survival of tumor cells." (PMID 33980886, 2021). "Taken together, our results suggest that Lpd mediates the glioblastoma radioresponse via the EGFR-MAPK-pathway." (PMID 34771501, 2021). "This reduction was observed in glioblastoma cells overexpressing wild-type EGFR or expressing mutant EGFRvIII." (PMID 34769339, 2021). "Noteworthily, a gene expression network modeling study reveals that necdin suppresses glioblastoma cell growth via molecular interaction networks involving EGFR." (PMID 34338396, 2021). "In glioblastoma, a specific imaging pattern was able to predict epidermal growth factor receptor (EGFR) overexpression." (PMID 33025328, 2021). "For example, a high EGFR expression is very common in glioblastoma multiforme (GBM) but its main feature is the limited efficacy of EGFR inhibitors." (PMID 33981532, 2021). "The epidermal growth factor receptor (EGFR) has been commonly found to be overexpressed in glioblastoma, and as a result, is a target for antibodies and peptides." (PMID 33440712, 2021). "For instance, in glioblastoma, Chloroquine delays tumor growth in epidermal growth factor receptor overexpressing glioblastoma xenografts, inhibits autophagy and is a potent radio-sensitizer." (PMID 34206772, 2021). "An example of this approach is the targeting of EGFR and its mutant form EGFRvIII, which are overexpressed in a large proportion of glioblastomas (GBMs)." (PMID 33946954, 2021). "In Shai’s dataset, the expression of EGFR was 3.815 times higher in glioblastoma tissues than in normal tissues." (PMID 33892666, 2021). "EGFR gene amplification and mutations in the EGFR variant III (EGFRvIII) gene can be utilized for glioblastoma therapy by using antibody drug conjugates (ADCs)." (PMID 34485282, 2021).
glioblastoma (continued). "Though it does not have any prognostic value, but its status can be helpful in glioblastoma patients in order to provide EGFR vIII targeted therapy." (PMID 34582442, 2021). "It has also been shown to inhibit receptor tyrosine kinase pathways through targeting EGFR in glioblastoma." (PMID 33596914, 2021). "A novel monoclonal antibody (mAb) known as D2C7 reacts with both the wild-type epidermal growth factor receptor and (EGFRvIII) (both of which are major glioblastoma driver oncogenes) overexpressed on the surface of cancer cells." (PMID 34582442, 2021). "Inhibition of DYRK1A in glioma cells destabilizes EGFR and reduces EGFR-dependent glioblastoma growth." (PMID 34117217, 2021). "CAR T cells can target glioblastoma-specific antigens, including interleukin-13 receptor subunit alpha-2 (IL-13Rα2), EGFR wt, and EGFRvIII, and are thus effective against glioblastoma in preclinical models." (PMID 33572835, 2021). "Human epidermal growth factor receptor (EGFR) and the EGFR variant (v) III mutation (EGFRvIII) are exosomal biomarkers that have been used for the early detection of fatal brain tumor glioblastoma from circulating blood." (PMID 34940275, 2021). "EGFRvIII-specific CAR-T cells were unable to eliminate heterogeneous glioblastoma but led to the proliferation of EGFRvIII-/EGFR+ glioblastoma cells." (PMID 33921581, 2021). "It has been shown that the uPA receptor, uPAR, can transactivate EGFR and that both uPA and uPAR participate in the resistance mechanisms towards anti-EGFR treatment in glioblastoma." (PMID 33886813, 2021). "Treatment using epigenetic regulators, alone or in conjunction with EGFR inhibitors, offers a new hope for glioblastoma patients." (PMID 34638714, 2021). "An immunotherapeutic strategy based on the adoptive transfer of genetically modified T-cells redirected to destroy EGFR vIII in glioblastoma cases has also been developed." (PMID 34582442, 2021). "Taken together, amplification and mRNA overexpression of LANCL2 and EGFR, and their co-amplification and co-expression were frequent in glioblastoma patients." (PMID 34461927, 2021). "In human glioblastoma derive cells, P4 increased the expression of EGFR and cyclin D1 through its PR and the recruitment of steroid receptor coactivator-1 (SRC-1)." (PMID 33752729, 2021). "Abnormalities in epidermal growth factor receptor (EGFR) are common, with a 30% to 60% rate of aberrancy in glioblastomas alone." (PMID 34405064, 2021). "EGFR amplification occurs in approximately 40–50% glioblastomas, which results in an increase in prosurvival and proliferative signals." (PMID 33980886, 2021). "The siRNAs against both epidermal growth factor receptor (EGFR) and PD-L1 were jointly delivered to glioblastoma cells." (PMID 33921892, 2021). "For example, doxorubicin-loaded minicells targeting epidermal growth factor receptors (EGFR) via Vectibix have been evaluated in a phase I clinical trial in adults with recurrent glioblastoma." (PMID 34884780, 2021). "Taken together, these data indicate a novel regulatory network between Lpd, RICTOR and EGFR in glioblastoma that jointly determines cell fate upon X-ray irradiation." (PMID 34771501, 2021). "These glioblastoma molecular subgroups are classified as G1/EGFR, G2/FGFR3, G3/NF1, G4/RAF, G5/PDGFRA, G6/Multi-RTK, and G7/Other." (PMID 34572759, 2021). "Another study on glioblastoma found that stable inactivation of EGFR induced a mesenchymal to epithelioid transition in EGFR-amplified xenografts, thereby affecting the aggressiveness of tumor cells." (PMID 34178679, 2021). "EGFR-CAR-transduced NK-92 cells have significantly greater cytotoxic activity against EGFR positive glioblastoma cell lines compared to mock-transduced NK cells." (PMID 33923528, 2021). "NK CARs targeting EGFR, derived from both NK-92 cells and primary NK cells from healthy donors, demonstrated activity against glioblastoma cell lines." (PMID 33923528, 2021).